RIN1 (Ras and Rab interactor 1)
Description:
Ras effector protein, which may serve as an inhibitory modulator of neuronal plasticity in aversive memory formation. Can affect Ras signaling at different levels. First, by competing with RAF1 protein for binding to activated Ras. Second, by enhancing signaling from ABL1 and ABL2, which regulate cytoskeletal remodeling. Third, by activating RAB5A, possibly by functioning as a guanine nucleotide exchange factor (GEF) for RAB5A, by exchanging bound GDP for free GTP, and facilitating Ras-activated receptor endocytosis.
Tractability: Antibody: its Gene Ontology location is reachable by antibodies, with high confidence. PROTAC: ubiquitination databases record sites on it; its protein half-life has been measured; a small molecule that binds it is known.
Gene: Protein-coding gene on chromosome 11 (66,330,241 to 66,336,840, reverse strand). Ensembl gene ENSG00000174791.
Subcellular location: Cytoplasm; Membrane; Cytoplasm, cytoskeleton
Pathways (Reactome):
Vesicle-mediated transport: RAB GEFs exchange GTP for GDP on RABs
Gene Ontology:
Molecular function: protein binding; small GTPase binding; guanyl-nucleotide exchange factor activity
Biological process: intracellular signal transduction; signal transduction; vesicle-mediated transport
Cellular component: cytoplasm; plasma membrane; cytosol; endocytic vesicle; cytoskeleton; membrane
Genetic constraint (gnomAD): Loss-of-function variants: 49 observed, 50.97 expected, observed/expected ratio (o/e) 0.96, 90% interval 0.76 to 1.22. The synonymous counts are far from expectation, so gnomAD's model fits this gene poorly and the ratio says little. Missense variants: 959 observed, 820.59 expected, observed/expected ratio (o/e) 1.17, 90% interval 1.11 to 1.23. Synonymous variants: 458 observed, 372.06 expected, observed/expected ratio (o/e) 1.23, 90% interval 1.14 to 1.33.
Homologues: Orthologues: chimpanzee RIN1 (99% identical), macaque RIN1 (96% identical), dog RIN1 (83% identical), guinea pig RIN1 (80% identical), mouse Rin1 (79% identical), rat Rin1 (79% identical), tropical clawed frog rin1 (39% identical), zebrafish rin1a (34% identical), zebrafish rin1b (31% identical), Drosophila melanogaster spri (24% identical), Caenorhabditis elegans rin-1 (23% identical), Caenorhabditis elegans rabx-5 (9% identical), and 1 more. Paralogues in human: RIN2 (31% identical), RIN3 (27% identical), RINL (17% identical), GAPVD1 (17% identical), VPS9D1 (13% identical), RABGEF1 (11% identical).
Diseases named in the same sentence as RIN1 in open-access papers:
RIN1 is named in the same sentence as 27 diseases in open-access papers, as found by Europe PMC text mining. Sharing a sentence is not in itself a finding about the gene and the disease. The quoted sentences say what the papers report.
breast carcinoma (7 papers, 2014 to 2022). "In an in vivo screen with breast cancer cells mutagenized with a replication-incompetent gammaretroviral vector, SHARPIN and RIN1 were described as novel breast cancer metastasis genes." (PMID 36497409, 2022). "The pathological significance of MAD2L1 in breast cancer; the metastasis promotion of PITPNC1 by melanoma, breast cancer, and colon cancer cells; and the suppression of breast tumors by RIN1 have also been reported." (PMID 33519944, 2021). "RIN1 was identified as a breast cancer tumor suppressor gene." (PMID 27792127, 2016). "Additionally, C21ORF123 promoter methylation has been implicated in cisplatin resistance in non-small cell lung cancer and RIN1 is a tumor suppressor that is deregulated through aberrant promoter methylation in breast cancer." (PMID 25472429, 2014). "However, for breast cancer, DNA methylation with RIN1 promoter was involved in silencing its expression, which may contribute to adenocarcinoma progression." (PMID 29079774, 2017). "In invasive ductal breast carcinomas, the expression of PTPN14 is lower (threefold) in comparison to ductal carcinomas, and the survival of breast cancer patients decreased if the tumors expressed high levels of the PTPN14 substrates, RIN1 or PKC-δ." (PMID 32152405, 2020). "A γRV shuttle vector approach identified previously known (WWTR1, RIN1) and also novel (SHARPIN) breast cancer metastasis genes." (PMID 27792127, 2016). "Four genes WWTR1, RIN1, MAF1 and SHARPIN were identified having significant expression levels in breast cancer patients by meta-analysis." (PMID 27792127, 2016).
breast tumor (4 papers, 2015 to 2024). "Marc Milstein reported that RIN1 gene was silenced in breast tumor cell lines compared to cultured human mammary epithelial cells and DNA methylation within the RIN1 promoter contributed to silence of the gene." (PMID 26207381, 2015). "Also, RIN1 has been identified as a breast tumor suppressor gene." (PMID 26506596, 2015).
glioma (3 papers, 2018 to 2023). A benign or malignant brain and spinal cord tumor that arises from glial cells (astrocytes, oligodendrocytes, ependymal cells). "When GII/GIII-IDHmut gliomas were compared to GIV gliomas, significant differences of DNA methylation in the promoters of S100A2, RAB36, RIN1, UPP1, and VIM were found." (PMID 36850002, 2023). "We performed RIN1 treatment of our glioma cells, and while RIN1 did not have a noticeable effect on RBPJ expression, RIN1-treated XIII, XIII-WT, and XVII cells exhibited significantly reduced cell viability." (PMID 32647372, 2020).
melanoma (3 papers, 2014 to 2021). A malignant, usually aggressive tumor composed of atypical, neoplastic melanocytes. "High RIN1 expression is related to tumor progression and poor prognosis in bladder urothelial carcinoma, gastric adenocarcinoma, melanoma and non-small cell lung cancer." (PMID 30905893, 2019). "We were also able to assess the efficacy of chemotherapy, as the proteomic profile evidenced only in responder patients the down regulation of 3 peaks which could belong to molecules involved in the regulation of melanoma apoptosis machine like RIN1." (PMID 25437182, 2014). "The expression of Ras and Rab interactor 1 (RIN1) expression increases and is related to poor prognosis in many tumors, including non-small cell lung cancer, melanoma, gastric adenocarcinoma and renal cancer." (PMID 30905893, 2019).
non-small cell lung carcinoma (3 papers, 2014 to 2024). A group of at least three distinct histological types of lung cancer, including non-small cell squamous cell carcinoma, adenocarcinoma, and large cell carcinoma. "In contrast, RIN1 expression levels were reported to be elevated in various tumors, including gastric adenocarcinoma, colorectal cancer, non-small cell lung cancer, and bladder urothelial carcinoma." (PMID 38635569, 2024).
colorectal cancer (2 papers, 2023 to 2024). A primary or metastatic malignant neoplasm that affects the colon or rectum. "CircRNA_102209 facilitated cell growth and development in colorectal cancer via targeting miR-761 to increase the RIN1 expression." (PMID 37020694, 2023). "From their study, RIN1 was found in the cytoplasm of colorectal cancer." (PMID 38635569, 2024).
asthma (1 paper, 2022). "Our findings and previous studies indicate that allelic variations in rs117996675 affect airway remodeling by ABL through different expression of RIN1 in late-onset asthma." (PMID 35432474, 2022). "This information supports that the regulation of RIN1 and BRMS1 is involved in the disease progression of asthma via allelic variations in rs117996675." (PMID 35432474, 2022).
bipolar disorder (1 paper, 2016). A disorder of the brain that causes unusual shifts in mood, energy, activity levels and the ability to carry out day-to-day tasks. "Few changes were identified following this treatment, although four proteins—FAM163A, RIN1, mTOR and MCCC1—shown to be dysregulated in bipolar disorder were dysregulated in the same direction by haloperidol treatment, suggesting that these effects may have been drug treatment-related." (PMID 27898073, 2016).
gastric cancer (1 paper, 2020). A primary or metastatic malignant neoplasm involving the stomach. "Among them, miR‐761 is able to inhibit RIN1 signaling and regulate the development of gastric cancer, thus it is selected for further study." (PMID 32706154, 2020).
glioblastoma (1 paper, 2012). The most malignant astrocytic tumor (WHO grade IV). "RIN1, the best characterized of the RIN paralog family, showed highest expression in glioblastoma cells and low but detectable expression in epithelial cells but was undetectable in the mast cell lines." (PMID 23185384, 2012).
head and neck malignant tumor (1 paper, 2024). "Association between high and low RIN1 expression and clinicopathologic characteristics in patients with head and neck malignant tumor." (PMID 38635569, 2024).
mantle cell lymphoma (1 paper, 2021). Mantle cell lymphoma is a rare form of malignant non-Hodgkin lymphoma affecting B lymphocytes in the lymph nodes in a region called the ``mantle zone''. "RIN1 inhibited RBP-Jk transcription and interaction with NICD, thereby reducing proliferation in T-ALL and mantle cell lymphoma (MCL) cell lines." (PMID 34422814, 2021).
renal cell carcinoma (1 paper, 2019). "RIN1 is associated with renal cell carcinoma aggressiveness." (PMID 30905893, 2019).
retinoblastoma (1 paper, 2020). A malignant tumor that originates in the nuclear layer of the retina. "miR-3619-5p is involved in LINC00202-mediated retinoblastoma progression through targeting the expression of an oncogene RIN1." (PMID 31915027, 2020).
tumor (15 papers, 2014 to 2025). "RIN1 expression has already been implicated in tumor development and invasion." (PMID 32735660, 2020). "RIN1 is involved in tumor metastasis and development but to our knowledge, there is no study on the level of RIN1 in head and neck tumors especially in Ghana." (PMID 38635569, 2024). "Fifteen of the patients had poor differentiated tumor with low expression of RIN1 out of 16 poorly differentiated tumors." (PMID 38635569, 2024). "Meanwhile, we also found that RIN1 inhibited tumor growth and improved the activity of CD8+ T cells." (PMID 36717584, 2023). "To confirm that RIN1 indeed improved the function of tumor-infiltrating CD8+ T cells by inhibiting PD-L1 expression and reducing L-kynurenine secretion, we performed in vivo recovery experiments." (PMID 36717584, 2023). "In vivo experiments confirmed that PD-L1 also reduced the antitumor effect of RIN1, including increased tumor growth and upregulated PD-1/TIM3 expression on CD8+ T cells." (PMID 36717584, 2023). "It is also possible that RIN-1 affects the characteristic “tumour cell plasticity”, often observed in advanced cancer cells and cell lines, and which is generally promoting processes such as invasion and motility." (PMID 37607974, 2023). "We adopted RIN1-stimulated CD8+ T cells in vitro (CD8+ TRIN1) into mice with HCC to evaluate their role in regulating tumor growth." (PMID 36717584, 2023). "The Danio rerio zebrafish model was used to investigate the anti-tumour potential of RIN-1 in in vivo conditions." (PMID 37607974, 2023). "In vivo experiments also confirmed that L-kynurenine reduced the antitumor effect of RIN1, including increased tumor growth and downregulated cytokine expression on mouse HCC infiltrating CD8+ T cells." (PMID 36717584, 2023). "Here we found that RIN1 expression was regulated by miR-3619-5p, and is an effector to mediate miR-3619-5p anti-tumor function." (PMID 30905893, 2019). "This study shows that miR-3619-5p also had a tumor suppressive function in RB, and RIN1 was identified as a new miR-3619-5p target." (PMID 30905893, 2019). "It has been reported that RIN1 overexpression aggravated tumor cells through activating EGFR signaling." (PMID 30905893, 2019). "Other CpGs are associated with genes related to immune function, including T cell regulation and inflammation, tumor initiation and angiogenesis (EBI3), while other genes have been implicated in cancer aggressiveness (AQP9, RIN1)." (PMID 25472429, 2014). "In both control and tumor samples, RIN1 protein was localized in the cytoplasm." (PMID 38635569, 2024). "We then attempted to analyze whether RIN1 could improve the anti-tumor immune response of CD8+ T cells in vitro." (PMID 36717584, 2023). "Particularly noticeable in this regard are the results obtained in non-adherent culture conditions, where a significant increase in the size and roundness of poorly differentiated tumour spheroids was observed that coincides with a putative induction or activation of Notch signalling by RIN-1." (PMID 37607974, 2023). "Our data revealed that hsa_circRNA_102209 was a novel oncogenic factor in CRC that could promote the growth and metastasis of tumor cells by suppressing miR‐761 and upregulating RIN1." (PMID 32706154, 2020). "The tumor lines had comparable levels of RBPJ protein; therefore, the varying effects of RIN1 on tumor cell proliferation might reflect differential reliance on RBPJ-dependent versus RBPJ-independent NOTCH signaling." (PMID 31346210, 2019). "Its transcription complex inhibitor RIN1 inhibited the occurrence and development of HCC by enhancing the activity of infiltrating leukocytes (especially CD8+ T cells) and inhibiting tumor cell proliferation and epithelial-mesenchymal transition." (PMID 36717584, 2023). "To simulate the interaction between tumor cells and CD8+ T cells, we co-cultured RIN1-treated HCC cells (HCCRIN1) or HCCRIN1 overexpressing PD-L1 (HCCRIN1 + PD-L1) with patient infiltrating CD8+ T cells, respectively." (PMID 36717584, 2023).
tumor (continued). "Several potential substrates for PTPN14, including β-catenin, p130Cas, RIN1 and PRKCD, and YAP, are all related to tumor progression and metastasis." (PMID 35135548, 2022). "RIN1 showed a stronger inhibitory effect on tumor growth than Hepa1-6Rbpj-KD, which suggested that RIN1 inhibition of tumor growth did not rely solely on blocking the assembly of RBPJ transcription complex in tumor cells." (PMID 36717584, 2023). "In contrast to CD8+ TRbpj-KD, CD8+ TRIN1 promoted tumor growth, and this positive effect was inhibited by anti-PD-1 antibody, indicating that RIN1 in vitro did not simulate the protective effect of CD8+ TRbpj-KD." (PMID 36717584, 2023). "However, treatment with RIN-1, an inhibitor of the RBPJ subunit of the NOTCH complex, significantly decreased SOX2 expression in tumor cells, suggesting that SOX2 expression regulated by NOTCH signaling may contribute to tumor development." (PMID 40128799, 2025).
cancer (6 papers, 2014 to 2024). A tumor composed of atypical neoplastic, often pleomorphic cells that invade other tissues. "RIN1 is a Ras effector protein regulating epithelial cell properties and has been implicated in a number of cancers." (PMID 38635569, 2024). "Thus, RIN1 was active in both the cancer cell anti-proliferation and myoblast differentiation assays." (PMID 31346210, 2019). "One molecule, termed RBPJ INhibitor-1 (RIN1), potently disrupted the functional interaction of RBPJ with NOTCH and functioned as a probe of RBPJ function in cancer and skeletal myogenesis models." (PMID 31346210, 2019). "RIN1 interacts with RAB5A, which is connected to genes that are involved in cancer cell epithelial-to-mesenchymal transition." (PMID 26515236, 2015). "Also, CB-103 was more effective than either DAPT or RIN1 in Jurkat and KOPT-K1, but not Rec1 lines, suggesting differential roles of the NOTCH pathway components across cancer lines with activating NOTCH mutations." (PMID 31346210, 2019).
Head and Neck Tumor (1 paper, 2024). "Using logistic regression analysis, we determined the clinicopathologic characteristics associated with high RIN1 expression in malignant Head and Neck Tumor." (PMID 38635569, 2024). "RIN1 transcript levels from head and neck tumors and normal head and neck tissues were also determined with real-time polymerase chain reaction (RT-PCR)." (PMID 38635569, 2024). "We also explored the correlation between the levels of RIN1 expression and clinical features such as gender, age and the anatomical site in head and neck tumor." (PMID 38635569, 2024). "High and low RIN1 levels were compared with ages ≤40, >40 in the head and neck tumors of p-value 0.02." (PMID 38635569, 2024). "In this research, we investigated the level of expression of RIN1 in head and neck tumors and normal tissues." (PMID 38635569, 2024). "From this present study, the level of expression of RIN1 is reduced or silenced in head and neck tumor tissues but was highly expressed in the normal head and neck tissues." (PMID 38635569, 2024). "From this present study, RIN1 was localized at the cytoplasm in the head and neck tumor tissues." (PMID 38635569, 2024). "This present study indicates that, the expression of RIN1 in head and neck tumors is low." (PMID 38635569, 2024). "Subsequently, we examined low levels of RIN1 protein in head and neck tumor tissues." (PMID 38635569, 2024). "The purpose of this study is thus to provide useful information about the level of RIN1 expression in head and neck tumors, which may provide baseline data to facilitate the identification of new molecular targeted therapeutics." (PMID 38635569, 2024). "The aim of this study was to investigate the expression of RIN1 in head and neck tumors." (PMID 38635569, 2024). "Understanding the expression and the localization of RIN1 in head and neck tumor is of great value in developing a novel therapeutic strategy." (PMID 38635569, 2024).
hematologic tumor (1 paper, 2019). "Consistent with disruption of NOTCH signaling, RIN1 inhibited the proliferation of hematologic cancer cell lines and promoted skeletal muscle differentiation from C2C12 myoblasts." (PMID 31346210, 2019). "As examples of its utility as a chemical probe, RIN1 suppressed the proliferation of three hematologic tumor cell lines (Jurkat and KOPT-K1 T-ALL, and REC-1 MCL)." (PMID 31346210, 2019).
RIN1 also shares sentences with these, for which no sentence is quoted: bladder urothelial carcinoma (2 papers); gastric adenocarcinoma (2); adenocarcinoma (1); colon cancer (1); colorectal (1); ductal carcinomas (1); invasive ductal breast carcinoma (1); renal carcinoma (1); salivary gland adenoid cystic carcinoma (1).